CD4 (CD4 molecule)
Diseases named in the same sentence as CD4 in open-access papers (continued):
Sharing a sentence is not in itself a finding about the gene and the disease.
AIDS (continued). "Our goal is to jointly model the CD4 count evolution since treatment initiation (ART), the visiting process, and competing risks (death or AIDS onset and disengagement from care)." (PMID 39449049, 2024). "In contrast, differences were found for the HIV route of transmission (p < 0.001), CD4+ cell count at ART initiation (p = 0.012), history of AIDS (p = 0.025), and poor previous adherence to ART (p = 0.001)." (PMID 38999501, 2024). "The CD4/CD8 ratio is used as an indicator of immune function and has been studied in various contexts, including HIV/AIDS, autoimmune diseases, and cancer." (PMID 38428854, 2024). "Cox proportional hazard models were used to analyse relationships between baseline characteristics (age, history of AIDS, HIV‐1 RNA, CD4 count, race, sex and study), blips and VF (strict definition of two consecutive HIV‐1 RNA ≥50 copies/ml after suppression)." (PMID 39513741, 2024). "A systematic review and meta-analysis covering 13 observational studies found significantly reduced mortality and progression to AIDS and significantly increased immunologic recovery among ART initiators with baseline CD4 counts greater than 500 cells/mm3." (PMID 38500055, 2024). "LPAD was defined as having an AIDS diagnosis within three months of initial HIV diagnosis, and delay time from HIV infection to diagnosis was estimated using CD4 depletion model." (PMID 38896338, 2024). "We found a low CD4 count at ART initiation, a previous AIDS-defining condition and transmission through intravenous drug use to be meaningful prognostic factors of the outcome." (PMID 38381307, 2024). "The search was conducted in PubMed and Web of Science using the terms: "health-related quality of life", "HQRoL", "HIV", "AIDS", "advanced HIV disease" and "low CD4 cells"." (PMID 38743382, 2024). "It is well known that optimal management of AIDS-related PCNSL requires controlling the HIV viral load and CD4 count with HAART." (PMID 39957858, 2024). "Individuals with a CD4 count below 200 cell/mm3, indicating advanced HIV/AIDS progression, had a significantly higher likelihood of being infected with intestinal parasites." (PMID 38755680, 2024). "We compared two cohorts of consecutive symptomatic AIDS patients (WHO stage 4, CD4 count<50 cells/mL) starting therapy with DTG-based (2018–2021, prospective cohort) or EFV-based regimens (2013–2016, retrospective cohort) from five Brazilian cities." (PMID 38482527, 2024). "Based on the findings of this study and existing literature, we assume that optimal adherence to ART play is of paramount importance to improve CD4 count and suppress the viral load of HIV/AIDS orphans." (PMID 39217361, 2024). "Since 1997, the Brazilian national AIDS program has provided free antiretroviral therapy (cART) for individuals infected with HIV, initially for patients with a CD4+ T cell count below 350 cell/mm3 and/or with opportunistic diseases." (PMID 38324873, 2024). "The CD4+/CD8+ ratio has been proposed as a suitable marker of persistent immune dysfunction and of the occurrence of non-AIDS-related events in treated patients with HIV13,14." (PMID 38324873, 2024). "The degree of immunosuppression, characterized by CD4 count and viral load, is also critical when evaluating patients with HIV/AIDS for infection." (PMID 39295724, 2024). "At enrolment, the median duration of HIV diagnosis was 4.9 months (IQR 2.3, 7.7), the median nadir CD4 count was 346 cells/μL (IQR 224, 494), median log HIV RNA was 4.08 copies/mL (IQR 2.04, 4.76), and 38% had an AIDS diagnosis." (PMID 36715051, 2023). "Hyperactive immune response with the proliferation of CD4+ and CD8+ T cells and their eventual death results in progress to AIDS." (PMID 37214076, 2023). "Next, we analyzed the correlation between CD4 count or pVL at pre-cART and the frequency of T-cell responses to HIV-1 epitopes under cART in 12 AIDS patients." (PMID 37877716, 2023).
AIDS (continued). "For the exemplification in Section 1, a 48-year-old male AIDS patient with a baseline CD4+ lymphocyte count of 395 cells/mm3, CD4% of 13.6%, CD8+ lymphocyte count of 1641 cells/mm3, and a CD4/CD8 ratio = 0.24 was randomly selected." (PMID 36769822, 2023). "The median nadir CD4+ T-cell count was 142 cells/mm3 (IQR, 35; 244 cells/mm3), the current CD4+ T-cell count was 237.5 (IQR, 79; 404), the baseline median CD4+/CD8+ ratio was 0.82 (IQR 0.58; 1.14) and 27% had a history of AIDS." (PMID 38065995, 2023). "Independent risk factors for severe outcomes (COVID-19-related hospitalization and death) were higher age, having multiple comorbidities, a CD4+ cell count less than 200 cells/μl, uncontrolled HIV replication, and prior AIDS diagnosis." (PMID 37199566, 2023). "Participants all took antiretroviral therapy (ART) and were mostly middle-aged (median age 44.0 years) men (78.8%), with AIDS (77.0%), plasma HIV RNA ≤ 200 copies/mL (75.8%), and immune recovery (median CD4+ T-cell count 414/μL)." (PMID 36769155, 2023). "In the AIDS group, there was significant correlation with LVH and lower BMI adjusted for age r = 0.20, CI= (0.09, 0.25) and lower CD4 cell count r = 0.09, CI= (0.03, 0.12) and increased pulse rate r = -0.015, CI= (- 0.01, 0.03)." (PMID 37719061, 2023). "After adjusting for other risk factors, mortality in all categories analysed was similar for sex, viral load, CD4/CD8 ratio, or AIDS diagnosis at enrolment." (PMID 38008809, 2023). "Third, these cohort results strengthen the results of the TANGO trial, and last but not least, it suggests a potential immunological benefit in increasing CD4+ lymphocyte count and CD4+/CD8+ ratio independently of age, sex, HIV stage, and pre-existing AIDS." (PMID 36851536, 2023). "We explore whether individuals starting ART with <500 CD4 cells/μL who increased their CD4 count above this level, have, from this point onwards, similar risk of clinical progression to serious AIDS/non-AIDS events or death with individuals starting ART with ≥500 CD4 cells/μL." (PMID 36996018, 2023). "At the same time, the introduction of ART at this stage can prevent the development of AIDS by suppressing HIV replication, which leads to a decrease in viral load and an increase in the number of CD4 + T-lymphocytes." (PMID 37048145, 2023). "Antiretroviral therapy (ART) provides an effective method for managing HIV-1 infection and preventing the onset of AIDS; however, it is ineffective against the reservoir of latent HIV-1 that persists predominantly in resting CD4+ T cells." (PMID 38140588, 2023). "CD4+ T cell count and HIV-1 viral load are two important predictors of HIV/AIDS disease progression and are used to determine the initiation and evaluate the efficacy of highly active antiretroviral therapy (HAART)." (PMID 38275941, 2023). "Depletion of CD4 + T cells and aberrant immune activation are typical features of HIV-1 infection, closely related to non-AIDS-defining disorders." (PMID 37705002, 2023). "Our cohort represents the general condition of PLWHIV in high-income countries, nevertheless a larger study on people with Low CD4+ T cells, uncontrolled HIV and AIDS would be beneficial to describe a more complete scenario." (PMID 36717688, 2023). "Third limitation is missing of measuring some important variables such as the prevalence of those PLHIV who had a history of AIDS, and what the pre-ART CD4 count was." (PMID 37093810, 2023). "A total of 466 participants (48.0%) had experienced an AIDS event before enrolment in the cohort; 960/970 (99.0%) had HIV RNA levels <200 copies/mL, and the median CD4 cell count was 509 (IQR,365–684)." (PMID 36800379, 2023). "Longitudinal data on 254 HIV/AIDS patients who received ART between 2009 and 2014, and who had at least one CD4 count observed, were employed in a Bayesian joint model of disease progression." (PMID 36691645, 2023).
AIDS (continued). "There were 37 PLWHA with CD4 count < 200 cells/μL (AIDS group) and 68 PLWHA with CD4 count ≥ 200 cells/μL (HIV + group)." (PMID 37102652, 2023). "This is also the case of the 2F5 region of gp42 of HIV/AIDS that induces IgA2 and IgG1 antibodies, which act synergistically, blocking the transfer of HIV-1 from Langerhans to autologous CD4+ T cells and inhibiting CD4+ T cell infection." (PMID 38140154, 2023). "CD39+ Treg cells are inversely correlated with CD4+ T cell count in HIV-infected patients, suggesting that CD39 is crucial in AIDS progression." (PMID 36839551, 2023). "An analogous scenario exists in the context of HIV infection progressing to AIDS, which results from the interaction between HIV viruses and the host CD4." (PMID 38239718, 2023). "At entry, median age was 46 years (IQR: 37–52), median CD4+ T-cell count was 566 cells/μL (IQR: 357–822), and 202 (20.3%) patients had a history of AIDS diagnosis." (PMID 37434782, 2023). "The level of CD4 count and stage of HIV/AIDS disease has also been shown to influence the development of PCL and CCa." (PMID 37113726, 2023). "The primary outcome was a composite of time-to-first of confirmed CD4 count below 350 cells/μL, initiation of ART, AIDS-defining illness or death." (PMID 35834528, 2022). "We recommended strengthening Bangladesh’s HIV/AIDS prevention, treatment, and management program with a special focus on the improvement of the supply chain of ART-related medicines and CD4 tests and ensuring proper counselling." (PMID 36269716, 2022). "Moreover, we recently showed that switching to dual therapies could be associated 6 months later with a significant increase in sCD163, a well-known marker of macrophage activation, in subjects with a low CD4 nadir, previous AIDS, or residual viremia during follow-up." (PMID 35632669, 2022). "In people living with HIV/AIDS (PLWHA), initiation of antiretroviral therapy (ART) leads to sustained effective suppression of viral replication and increasing CD4 + T cell count." (PMID 35114959, 2022). "In contrast, CD8/CD4 cell ratios, as high as 4:1, are needed to suppress 90% of the HIV replication in CD4 T cells from AIDS patients." (PMID 36172358, 2022). "A low CD4/CD8 ratio could be interpreted as the epiphenomenon of a dysregulation and immunological activation of patient’s immune system with hyperinflammation and immunosenescence, and has been associated with non-AIDS-defining events, mortality, and premature aging." (PMID 36366413, 2022). "Women have higher CD4+ T cell counts, and lower HIV plasma RNA loads during the asymptomatic phase of infection, but both males and females progress to AIDS at similar rates." (PMID 35693831, 2022). "This CD4+:CD8+ ratio inversion could be partially rescued by the administration of antiretroviral therapies (ART) that inhibit viral replication, CD4+ T-cells progressive loss and AIDS development in most infected individuals, although they do not lead to complete viral clearance." (PMID 35955721, 2022). "PLWH are also queried about nadir CD4+ levels, date of HIV diagnosis, history of AIDS and non-AIDS-defining illnesses, history of and current use of ART, and cumulative duration of ART use." (PMID 38455337, 2022). "Data on CD4+ T cell count at HIV diagnosis and death from AIDS within one year after first HIV diagnosis were used to distinguish recent HIV infections." (PMID 35732657, 2022). "The ARL‐IPI based on the base‐line characteristics of ECOG performance status, LDH level, stage, number of involved extranodal sites (ENS) and an HIV score that incorporates base‐line CD4 count, HIV viral load and prior history of AIDS." (PMID 36056692, 2022). "In this way, tuberculosis delays the recovery of CD4 T-cells that are also destroyed by HIV, which increases the progression of the disease to AIDS and, consequently, the deaths from tuberculosis in PLHIV." (PMID 35655177, 2022).
AIDS (continued). "CD4+ cell count recovery after effective antiretroviral therapy (ART) is an important determinant of both AIDS and non-AIDS morbidity and mortality." (PMID 35324948, 2022). "The long-lived HIV reservoir, including latently infected resting memory CD4+ T cells, is considered one of the major obstacles to an HIV/AIDS cure." (PMID 35038908, 2022). "In essence, research on HIV/AIDS has unveiled that HIV targets the immune cells, specifically CD4 T-cells." (PMID 35632825, 2022). "The infection of CD4 T-lymphocytes with human immunodeficiency virus (HIV), the etiological agent of acquired immunodeficiency syndrome (AIDS), disrupts cellular homeostasis, increases oxidative stress and interferes with micronutrient metabolism." (PMID 35163318, 2022). "To reduce and minimize the impact of FRR in the LAg Avidity assay, we collected data on CD4+ T cell count at HIV diagnosis and death from AIDS within one year after the first HIV diagnosis for specimens used in the study." (PMID 35732657, 2022). "The literature indicates a short-term weight gain in HIV/AIDS patients who begin ART, particularly those with a low pretreatment BMI and significantly low CD4 at the time of ART initiation." (PMID 35603131, 2022). "Unfortunately, this often happens at the stage of symptomatic AIDS in late presenters, defined as a new HIV infection with a low CD4 count (<350 cells/μL) or the onset of an AIDS-defining clinical condition, regardless of the CD4 count." (PMID 35208594, 2022). "Previous studies have documented correlations of suicidal behaviors and HIV-related clinical features, including low CD4 cell counts, suspension of ART, and the presence of an AIDS diagnosis." (PMID 35400050, 2022). "Co-occurrence of TB and HIV is a medical emergency, with the adverse outcomes of these infections including pancytopenia and low levels of CD4 and CD8, which contribute to the progression of AIDS." (PMID 35846073, 2022). "Moreover, PLWH with CD4 T-cell count below 200 cells/μL, a threshold for increased risk of AIDS, may not respond well and durably to vaccine, as previously reported for other vaccines." (PMID 35098197, 2022). "Patients with HIV/AIDS and CD4 cell count of ≤200 cells/mm3 were nearly six times [AOR: 4.72, 95% CI: (2.14–12.13)] more likely undernourished than patients with a CD4 cell count of ≥500 cells/mm3." (PMID 36618702, 2022). "Syphilis infection can decrease CD4 cell counts and increase virus replication in HIV/AIDS patients." (PMID 34678871, 2021). "Lastly, we explored the association between time from HIV diagnosis to ART initiation and AIDS-related mortality in HIV/AIDS patients with high and low CD4+ cell counts." (PMID 34592916, 2021). "The model used data on HIV and AIDS diagnoses routinely collected via the national HIV and AIDS Reporting System in England, and knowledge on the progression of HIV through CD4-defined disease stages." (PMID 34118196, 2021). "While the role of CD4 count in managing HIV patient care is diminished, it remains an important prognostic marker for modelling disease progression, AIDS‐related death and care seeking." (PMID 34546644, 2021). "Age, educational status, family size, alcohol consumption, tobacco and chat usage, baseline and current weight, baseline CD4 cell count, baseline hemoglobin, and tuberculosis (TB) diseases were all significant predictors of survival of HIV/AIDS patients." (PMID 33941074, 2021). "CXCR4-using viruses are thought to accelerate depletion of CD4 T lymphocytes (CD4TL) and AIDS development." (PMID 33872329, 2021). "The natural course of HIV-1 infection results in the destruction of CD4+ T lymphocytes (CD4TL), the onset of AIDS and death from opportunistic infections." (PMID 33872329, 2021). "Comparison between the recovered CD4+ T-cell count post-cART treatment, and the baseline CD4+ T-cell count is necessary for monitoring the dynamic CD4+ T-cell count and optimizing the level of immune function in patients with HIV/AIDS." (PMID 34326884, 2021).
AIDS (continued). "There were some differences in models results for the historical period in estimates of trends in mortality that were mostly due to assumptions about non-AIDS mortality and the effects of ART on CD4 counts." (PMID 34662333, 2021). "AIDS is defined as the most severe stage of HIV infection, diagnosed with a CD4+ T cell count of fewer than 200 cells/mm3." (PMID 33451365, 2021). "The CD4-staged back-calculation approach reconstructs HIV incidence and estimates time-varying diagnosis rates by use of information on new HIV and AIDS diagnoses, CD4 cell counts around diagnosis, and the natural course of HIV infection." (PMID 34118196, 2021). "Both algorithms update the coefficients referring to the longitudinal CD4 cell profile and the variable prevOI right away and therefore see a strong connection between the risk for death and the CD4 cell count as well as whether or not a patient has AIDS." (PMID 34819988, 2021). "The results suggested that autologous bone marrow transfusion is effective in protecting CD4+T, CD8 + T, WBC, PLT, HB levels in AIDS patients who require treatment for concomitant ARLs." (PMID 33509081, 2021). "About 5% of them had a CD4 cell count of less than 200 cells/mm3 and the majority (75.7%) fell under the III/IV stage of WHO HIV/AIDS clinical division." (PMID 34200010, 2021). "Previous studies have demonstrated that TCM can increase CD4+ T-cell counts and improve the immunological function of patients with HIV/AIDS, but most of these studies were small, with low sample sizes and short observation times." (PMID 34326884, 2021). "With differentiated CD4+ T cells as its primary target, HIV infection progressively deteriorated human immune system through three major phases: primary, chronic, and AIDS." (PMID 34804062, 2021). "If true, measurement of perforin-mediated cytotoxicity might be a better quantification of cellular immunity than measurement of total CD4+ and/or CD8+ T cells as a predictor for risk of development of HCMV retinitis in various immunosuppressed patient populations including patients with AIDS." (PMID 34358000, 2021). "The 30.4% (28/92) of patients were in AIDS stage according to HIV CDC Classification, with a median of CD4+ T cell count of 247 cells/μL (IQR: 109—386 cells/μL); furthermore, 72% had CD4/CD8 ratio ≤ 0.20 and only 7.8% had an optimum CD4/CD8 ratio (≥ 8)." (PMID 34556049, 2021). "We have identified key indicators, trends, and predictors of CD4 and VL levels at diagnosis to inform about the HIV/AIDS epidemic in Mexico." (PMID 34774077, 2021). "In future studies, details of the dynamic changes in CD4+ cell counts and ART compliance should be considered in order to explore their influence on AIDS-related mortality." (PMID 34592916, 2021). "Besides, we found an association between CD4 count and hemoglobin level: anemia rate significantly increased in patients with low CD4 count, and low hemoglobin level increased the risk of death in patients with AIDS, independent of the CD4 count." (PMID 33860053, 2021). "Chronic activation of CD4 and CD8 T cells is an established correlate of progression to AIDS in both HIV and SIV infections." (PMID 33961680, 2021). "In particular, education on how to prevent HIV transmission, how to remain healthy in terms of suppressing their viral load and maintaining their CD4 counts, and the latest information on HIV/AIDS were the most salient to participants." (PMID 34444297, 2021). "The purpose of this analysis is to model the CD4 count of patients from KwaZulu-Natal, South Africa, as part of a comprehensive study of HIV/AIDS." (PMID 34504147, 2021). "At treatment initiation, the median age was 36 years (interquartile range [IQR]: 30; 44), median CD4 count was 420 cells/μL (IQR: 273; 596), 6.1% individuals had a history of an AIDS‐defining illness and 38.1% had a VL > 100,000 copies/mL." (PMID 34291580, 2021).